ATXN3 (ataxin 3)
Diseases named in the same sentence as ATXN3 in open-access papers (continued):
Sharing a sentence is not in itself a finding about the gene and the disease.
viral infection (2 papers, 2018 to 2020). "On the other hand, during viral infection, ATXN3 DUB activity protects HDAC3 from degradation to activate the interferon I pathway." (PMID 32581696, 2020). "ATXN3 also directly regulates the ubiquitination state of HDAC3 to modulate IFN-I antiviral activity during viral infection." (PMID 30231063, 2018). "Therefore, the role of ATXN3 in gene regulation might be related to cellular response to adverse conditions, such as viral infection and stress." (PMID 32581696, 2020).
amyloidoses (1 paper, 2013). "The specificity of binding with only fibrillar species associating with phosphorylated phospholipids provides a link between ataxin-3 and the growing evidence that soluble oligomers disrupt membranes as part of the mechanism of toxicity within amyloidoses." (PMID 23894474, 2013).
B-cell chronic lymphocytic leukemia (1 paper, 2017). "All three genes specific to the M3 subtype (ATXN3, thymine-DNA glycosylase (TDG, 12q24.1), and HCLS) also showed possible associations with cancer risks, such as B-cell chronic lymphocytic leukemia (B-CLL)." (PMID 28249600, 2017).
cervical adenocarcinoma (1 paper, 2026). An adenocarcinoma arising from the cervical epithelium. "ATXN3 was downregulated in human papillomavirus(HPV18+) cervical adenocarcinoma but upregulated in HPV16+ cervical squamous cell carcinoma." (PMID 41507147, 2026).
chronic gastritis (1 paper, 2015). Inflammation of the stomach that is chronic in nature. "We noticed that 6 somatic variations (ATXN3, PLIN4, PDZD2, MUC4, DMBT1 and DAB1) were simultaneously observed in triple samples of chronic gastritis, primary cancer and PM cancer." (PMID 26330360, 2015).
colon adenocarcinoma (1 paper, 2024). "While deubiquitinase ATXN3 has been implicated as a potential oncogene in various types of human cancers, its role in colon adenocarcinoma remains understudied." (PMID 38815863, 2024). "Immunohistochemical staining indicated a decrease in ATXN3 levels in human colon adenocarcinoma compared to those in healthy colon tissues, implying a tumor-suppressive role for ATXN3." (PMID 38815863, 2024). "Notably, quantitative analysis demonstrated a modest yet statistically significant reduction in both ATXN3 and Galectin-9 in malignant colon adenocarcinoma compared to adjacent normal colon tissues." (PMID 38815863, 2024).
colon adenoma (1 paper, 2024). An adenoma that arises from the colon. "Intriguingly, a robust positive correlation between ATXN3 and Galectin-9 was observed in both colon adenomas and adenocarcinomas, as expected; however, this correlation was absent in adjacent healthy colon tissues." (PMID 38815863, 2024).
fibrolamellar carcinoma (1 paper, 2022). "The mRNA expression of ATXN3 was significantly associated with different HCC subclasses, with hepatocellular carcinoma having the highest levels and fibrolamellar carcinoma showing the lowest levels." (PMID 36159990, 2022).
hepatocellular adenoma (1 paper, 2022). A benign epithelial neoplasm arising from the hepatocytes. "The sub-types of with the highest proprotion of all alterations were Hepatocellular carcinoma plus Intrahepatic Cholangiocarcinoma, Hepatocellular Adenoma, and Hepatocellular carcinoma for ATXN3, ATXN3L, JOSD1, and JOSD2, respectively." (PMID 36159990, 2022).
hepatocellular carcinoma (1 paper, 2022). A malignant tumor that arises from hepatocytes. "Furthermore, we analyzed the co-expression of ATXN3, JOSD1 and JOSD2 in hepatocellular carcinoma using the GSCALite database, and analyzed the signaling pathways involved by MJDs family member respectively." (PMID 36159990, 2022).
hereditary spastic paraplegia (1 paper, 2015). Hereditary spastic paraplegias (HSP) comprise a genetically and clinically heterogeneous group of neurodegenerative disorders characterized by progressive spasticity and hyperreflexia of the lower limbs. "Wang and co-workers identified CAG expansions in the ATXN3 gene of six Chinese subjects with hereditary spastic paraplegias (HSP)." (PMID 26331044, 2015). "Our findings of SCA3 Cuban patients with a phenotype similar to hereditary spastic paraplegia are in agreement with this report, supporting a consideration to analyse the ATXN3 gene in patients clinically diagnosed as HSP." (PMID 26331044, 2015).
idiopathic dystonia (1 paper, 2021). "Seven (10%) patients had confirmed genetic diagnosis (including THAP1, ADCY5, VPS41, ATXN3, AFG3L2, KMT2B), 12 (18%) had acquired causes and the remainder had idiopathic dystonia." (PMID 34437382, 2021).
Lewis lung carcinoma (1 paper, 2023). "CRISPR deletion of ATXN3 expression in Lewis lung carcinoma LLC1 cells resulted in a significant reduction in PD-L1 protein expression as detected by Western blotting and flow cytometry." (PMID 38038129, 2023). "We then used the LLC1 Lewis lung carcinoma syngeneic tumor model to test whether targeted ATXN3 suppression enhances antitumor immunity in C57BL/6 mice." (PMID 38038129, 2023).
lung adenocarcinoma (1 paper, 2023). A carcinoma that arises from the lung and is characterized by the presence of malignant glandular epithelial cells. "Importantly, ATXN3 expression was increased in human lung adenocarcinoma and melanoma, and its levels were positively correlated with PD-L1 as well as its transcription factors IRF1 and HIF-2α." (PMID 38038129, 2023). "Consistently, analysis of the The Cancer Genome Atlas (TCGA) database revealed a positive correlation between ATXN3 and CD274 expression in human lung adenocarcinoma." (PMID 38038129, 2023). "To further validate our findings in human cancers, we analyzed protein expression levels of ATXN3, PD-L1, IRF1, and HIF-2α in human lung adenocarcinoma tissue microarrays and melanoma tissue microarrays, which included 61 lung adenocarcinoma cases and 48 melanoma cases, respectively." (PMID 38038129, 2023). "Last but not least, ATXN3 positively correlated with expression of PD-L1 and its transcription factors HIF-2α and IRF1 in both human lung adenocarcinoma and melanoma tissues." (PMID 38038129, 2023).
lymph node metastasis (1 paper, 2022). "In the lymph node metastasis group, the mRNA expression levels of ATXN3 in both N0 and N1 groups were observably higher than that in the normal control." (PMID 36159990, 2022).
melanoma (1 paper, 2023). A malignant, usually aggressive tumor composed of atypical, neoplastic melanocytes. "A similar result was obtained when the B16 melanoma model was used, further supporting our conclusion that ATXN3 inhibition enhances checkpoint blockade therapy even with suboptimal anti–PD-1 treatment." (PMID 38038129, 2023). "Importantly, further analysis of CRISPR KO B16 melanoma cells confirmed that targeted suppression of ATXN3 and USP30 dramatically reduced PD-L1 expression." (PMID 38038129, 2023).
pancreatic cancer (1 paper, 2024). "A recent study has shown that ataxin-3 and HDAC6 co-immunoprecipitate and interact, as suggested by a previous surface plasmon resonance study, and overexpression of ataxin-3 promotes the deubiquitination of HDAC6 in pancreatic cancer cells." (PMID 38497605, 2024).
parkinsonian disorder (1 paper, 2025). A group of disorders which feature impaired motor control characterized by bradykinesia, MUSCLE RIGIDITY; TREMOR; and postural instability. "Other repeat expansion genes, including ATXN3, CACNA1A, and PRNP, typically associated with parkinsonian disorders, do not exhibit an association with PD in our cohort." (PMID 41009775, 2025).
progressive neurodegenerative disorder (1 paper, 2013). "SCA3 is a progressive neurodegenerative disorder caused by an expanded repeat within one allele of the gene encoding ataxin-3 (ATX-3) protein, and allele-selective inhibition can be achieved using duplex RNAs that target polymorphisms." (PMID 23935115, 2013).
testicular tumors (1 paper, 2022). "Our results showed that ATXN3, JOSD1, and JOSD2 were markedly up-regulated in HCC samples, while ATXN3L was expressed only in testicular and testicular tumors." (PMID 36159990, 2022).
thyroid cancer (1 paper, 2025). "Conversely, in pancreatic and thyroid cancers, ATXN3 expression is significantly upregulated, promoting malignant phenotypes, including cell proliferation, migration, and invasion." (PMID 40995818, 2025).
neurodegenerative disease (95 papers, 2010 to 2026). A disorder of the central nervous system characterized by gradual and progressive loss of neural tissue and neurologic function. "These degenerative disease-causing substitutions in p97 stabilize and greatly enhance its interaction with ATXN3, suggesting an inhibitory role." (PMID 38977901, 2024). "As one of the nine polyglutamine neurodegenerative diseases, SCA3 is caused by an abnormally expanded polyglutamine (polyQ) repeat in the ataxin-3 protein." (PMID 35851059, 2022). "SCA3 is an autosomal-dominantly inherited neurodegenerative disease which is caused by an expansion of CAG-repeats in exon 10 of the ataxin-3 (Atxn3) gene leading consecutively to a higher number of glutamines (polyQ) in the ataxin-3 protein." (PMID 33106888, 2021). "This neurodegenerative disease is caused by expansion of CAG triplet repeats in the MJD1 gene (also called ATXN3, ataxin-3)." (PMID 22934023, 2012). "One interpretation of this is that ataxin-3 contributes to pathology in other neurodegenerative diseases." (PMID 38497605, 2024). "Mutant polyQ-expanded ataxin-3 protein is prone to aggregation in affected neurons and is predominantly degraded by autophagy, which is beneficial for neurodegenerative disease treatment." (PMID 39765823, 2024). "As such, inroads made in relation to understanding the DUB function of ataxin-3 in MJD will likely also be important for understanding the pathophysiology of other diseases including neurodegenerative diseases and cancer." (PMID 38497605, 2024). "Because SCA3 is a monogenic neurodegenerative disease, the onset and progression of disease phenotypes are dependent upon both the CAG repeat size and the number of mutant ATXN3 alleles." (PMID 36875652, 2023). "ATXN3 has also been shown to play a role in DNA damage, a common pathological symptom of neurodegenerative diseases." (PMID 36010688, 2022). "Given the intriguing role of n-BP in autophagy and relieving neurodegenerative diseases, we evaluated the effect of n-BP on the ATXN3 with 84 glutamine repeats transgenic mouse models by animal behavior analysis and imaging approaches." (PMID 34199295, 2021). "Spinocerebellar ataxia 3 (SCA3, also known as Machado–Joseph disease) is a neurodegenerative disease caused by inheritance of a CAG repeat expansion within the ATXN3 gene, resulting in polyglutamine (polyQ) repeat expansion within the ataxin-3 protein." (PMID 34473252, 2021). "Ataxin-3 (ATX3) is one among several proteins containing stretches of consecutive glutamines that are responsible for different, albeit related, neurodegenerative diseases in humans, when their size exceeds a critical threshold." (PMID 29042637, 2017). "The protein ataxin-3 carries a polyglutamine stretch close to the C-terminus that triggers a neurodegenerative disease in humans when its length exceeds a critical threshold." (PMID 29042637, 2017). "Overall, our results provide a well-characterized MJD fibroblast resource for neurodegenerative disease research and contribute for the understanding of mutant ataxin-3 biology and its molecular consequences." (PMID 27328712, 2016). "IU1 was also shown to promote the degradation of several overexpressed proteins (tau, TDP‐43 and ATXN3) in various neurodegenerative diseases." (PMID 27028664, 2016). "Ironically, normal ATXN3 is involved in the regulation of protein aggregates and supposedly plays a role in the suppression of polyQ-related neurodegenerative diseases such as Huntington's disease." (PMID 25605410, 2015). "Ataxin-3 is a particularly interesting DUB because it plays a central role in a neurodegenerative disease, interacts with multiple ubiquitin ligases, and regulates ubiquitin chain production and proteasomal degradation of proteins." (PMID 25988170, 2015). "A unique example of a protein responsible for a polyQ neurodegenerative disease that is involved in ubiquitin-dependent proteasomal degradation is ataxin-3." (PMID 25132814, 2014).
neurodegenerative disease (continued). "Collectively, these findings suggest that spermidine can induce autophagy in the MJD zebrafish, aiding the clearance of mutant ataxin-3 protein species, and providing neuroprotective benefits, aligning with previous findings exploring the utility of spermidine for neurodegenerative diseases." (PMID 38443995, 2024). "Ataxin-3's role as a DUB enzyme may also serve an important neuroprotective function in other neurodegenerative diseases, such as ALS." (PMID 38497605, 2024). "ATXN3 has been linked to various types of cancer and neurodegenerative diseases; however, its roles in NB have not been established." (PMID 34322387, 2021). "In addition, ATXN3 has been identified as a potential therapeutic target for neurodegenerative diseases." (PMID 34322387, 2021). "Furthermore, our truncated ATXN3 model also revealed more mitochondrial fissions, suggesting that mitochondrial fission is a common characteristic of neurodegenerative diseases." (PMID 28676741, 2017). "IU1, a selective small molecule inhibitor of USP14, has been shown to accelerate proteasomal degradation of aggregation-prone proteins, including proteins associated with neurodegenerative diseases such as tau, TDP43 and the polyQ protein ataxin-3, as well as oxidized proteins." (PMID 25132814, 2014). "Alternatively, because such inclusions are thought to reflect cellular attempts at protection, this may suggest that ataxin-3's normal function is involved in dealing with aberrant, aggregated, and neurotoxic proteins in these neurodegenerative diseases in a protective manner." (PMID 38497605, 2024). "Additionally, ATXN3 is a potential therapeutic target in neurodegenerative disease." (PMID 26079537, 2015). "For example, by modulating linear ubiquitination, LUBAC induces proteasomal degradation of aberrantly aggregated proteins, including mutant Huntingtin, Ataxin-3, SOD1, and TDP-43, which all are involved in neurodegenerative disease." (PMID 34737388, 2022). "As a response to accumulation of misfolded ER proteins, the expression of gp78 is increased by accumulation of neurodegenerative disease proteins, such as mutant htt, SOD1, and ataxin-3." (PMID 20126661, 2010). "The sleep fragmentation we observed seems to be a common feature in neurodegenerative diseases and could, therefore, contribute to improper clearance of the misfolded and aggregation-prone mutant ATXN3 protein in SCA3." (PMID 36231095, 2022). "This hypothesis was already tested in several neurodegenerative diseases including MJD, where a direct correlation between the presence of mutant ataxin-3 fragments and disease severity was established." (PMID 34830171, 2021). "Ataxin-3 is a deubiquitinase (DUB) that is required for non-selective autophagy and that is linked to neurodegenerative disease." (PMID 31379806, 2019).
cancer (27 papers, 2014 to 2026). A tumor composed of atypical neoplastic, often pleomorphic cells that invade other tissues. "Future studies are needed to precisely dissect the underlying molecular mechanisms in regulating ATXN3 and Galectin-9 expression under biological conditions versus cancer." (PMID 38815863, 2024). "As aberrant deubiquitination has been linked to both neurodegeneration and cancer, a comprehensive understanding of ataxin-3's DUB function is important for elucidating potential therapeutic targets in these complex conditions." (PMID 38497605, 2024). "Ataxin-3 has also been implicated in the progression of numerous cancers including testicular, breast, gastric, and thyroid cancers." (PMID 38497605, 2024). "Analysis has found loss-of-function mutations and deep deletions of Ataxin-3 as well as Ataxin-3L in many cancers, such as uterine, bladder, lung, and cholangiocarcinoma cancer." (PMID 32982735, 2020). "• Ataxin-3 and Ataxin-3L are mutated in different cancers, mainly missense mutations that lead to amino acid substitutions." (PMID 32982735, 2020). "The most frequent alteration in Ataxin-3 and Ataxin-3L is mutation in different cancers, mainly missense mutations that lead to amino acid substitutions." (PMID 32982735, 2020). "The downstream signaling network of ATXN3 remains incompletely elucidated, though it is known to exert pleiotropic and context-dependent effects in cancer." (PMID 41507147, 2026). "Recent studies have indicated that ATXN3 plays a dual role in cancer (promoting or inhibiting), depending on the type of cancer and its molecular background." (PMID 40995818, 2025). "By analyzing cancer and neuronal cell models, we find that compromising ATXN3 function leads to a severe delay in clearing and regenerating damaged lysosomes and thus in restoring functionality of the lysosomal system after lysosomal damage." (PMID 40730717, 2025). "The reduction of ATXN3 results in the degradation of Galectin-9 protein, thereby impeding Galectin-9-induced apoptosis and promoting the progression of cancer." (PMID 38815863, 2024). "Galectin-9 is recognized for its tumor-suppressive roles, promoting cancer cell apoptosis and inhibiting cancer cell growth, suggesting a tumor-inhibitory role for the Galectin-9 deubiquitinase ATXN3." (PMID 38815863, 2024). "Crucially, the restoration of Galectin-9 expression completely countered the increase in ATXN3-null cancer cell growth, unequivocally demonstrating that ATXN3 executes its tumor-suppressive functions through the upregulation of Galectin-9." (PMID 38815863, 2024). "Using CRISPR-based screening, here we identified ATXN3 as, to our knowledge, the first deubiquitinase that promotes PD-L1 expression at the transcriptional level in cancer cells." (PMID 38038129, 2023). "Together with the fact that ATXN3 positively correlated with PD-L1 expression in more than 80% of human cancers, our study collectively shows that ATXN3 inhibition enhances antitumor immunity in a broad spectrum of cancers." (PMID 38038129, 2023). "Collectively, these observations indicate that ATXN3 promotes IFN-γ–induced PD-L1 transcription at least partially through the stabilization of its transcriptional factor IRF1 in cancer cells." (PMID 38038129, 2023). "In contrast, ATXN3 CRISPR deletion slightly reduced B16 but increased MC38 cell growth and colony formation in vitro, implying that ATXN3 plays a diverse role in different cancer types." (PMID 38038129, 2023). "Targeted deletion of ATXN3 in cancer cells largely abolished IFN-γ– and hypoxia-induced PD-L1 expression and consequently enhanced antitumor immunity in mice, and these effects were partially reversed by PD-L1 reconstitution." (PMID 38038129, 2023). "HAUSP/USP7, USP10, USP11, USP13, OTUD3, and Ataxin-3 have all been recently identified as PTEN DUBs that control PTEN activity in different cancer-specific contexts." (PMID 36385557, 2022).